EPCAM (epithelial cell adhesion molecule)
Diseases named in the same sentence as EPCAM in open-access papers (continued):
Sharing a sentence is not in itself a finding about the gene and the disease.
liver cancer (continued). "Interestingly, preliminary flow cytometry analysis demonstrated that TREM1 silencing significantly reduced the proportion of CD133+EpCAM+ liver cancer stem-like cells (LCSLCs)." (PMID 40677705, 2025). "Additionally, we employed cell line-derived xenograft (CDX) models and bulk RNA-sequencing to determine the role of TREM1 in CD133+EpCAM+ LCSLCs in liver cancer." (PMID 40677705, 2025). "Notably, transcriptional levels of c-Myc and EpCAM promoters in hepatic cancer cells were downregulated by the decreased level of SLC1A4, which was reversed by the transfection of the Flag-AKT plasmid." (PMID 39949345, 2025). "Although this phenomenon is well understood, the transcription factors that determine the metastatic fate of epithelial cell adhesion molecule (EpCAM)-positive epithelial liver cancer cells remain largely unknown." (PMID 40253402, 2025). "Similarly, in liver cancer studies, EpCAM expression correlates with cancer progression and patient survival, highlighting its potential for diagnosing and assessing liver cancer prognosis." (PMID 39184916, 2024). "They demonstrated elevated annexinV+ EpCAM+ CD147+ TMPs in liver cancers, including HCC and CCA." (PMID 38665948, 2024). "According to ClinicalTrials.gov, there is currently one registered trial (NCT02729493) recruiting patients with relapsed or refractory liver cancer for infusion of their own T cells that have been genetically modified to express a CAR targeting EpCAM-positive tumor cells." (PMID 39417449, 2024). "CD13 and CD326 (EpCAM) are well-established surface markers of cancer stemness in liver cancer." (PMID 36008383, 2022). "Moreover, induction of YAP1 by NOTCH can promote the expression of SOX9 and EpCAM stemness markers in liver cancer." (PMID 36045416, 2022). "For instance, cancer cells are defined as CD31−/CD45-/7-AAD- cells, and CSCs are defined as CD24+/CD133+/epithelial cell adhesion molecule (EpCAM)+ cells after immunofluorescence staining and sorting by flow cytometry in some single-cell analyses of liver cancer." (PMID 35574365, 2022). "We found that BJJP significantly reduced the expressions of CD24, CD133 and EpCAM in the liver cancer tissues, indicating BJJP could suppress the properties of CSCs in HCC." (PMID 34297271, 2022). "Also, patients‐derived OCT4, CD133 or EpCAM positive primary liver cancer cells displayed higher levels of GS expression than those negative cells." (PMID 35187863, 2022). "In addition, microRNA-181 has been identified as a vital player in EpCAM positive hepatic cancer stem cells." (PMID 34141708, 2021). "Herein, we investigated senescence‐associated stemness in EpCAM+/CD133+ liver cancer stem cell and EpCAM−/CD133− nonstem cell populations in HuH7 cell line." (PMID 33524223, 2021). "Furthermore, we found that the expression of JMJD2D, EpCAM, and Sox9 was upregulated in human liver cancer specimens in GEO database, and the mRNA levels of JMJD2D were positively correlated with EpCAM and Sox9 in TCGA database." (PMID 33434575, 2021). "Interestingly, HPC and liver cancer stem cells (CSCs) also share several cellular markers, such as EpCAM, CD133 and CD2414,15." (PMID 32382012, 2020). "Recent studies indicated that stem cell-related markers or signaling pathways, such as aldehyde dehydrogenase (ALDH), CD133, epithelial cell adhesion molecule (EpCAM), Wnt/β-catenin signaling, and Notch signaling, contribute to the initiation and progression of various liver cancer types." (PMID 32987767, 2020). "MYCN gene is overexpressed in restricted cell populations such as EpCAM+ CSCs in liver cancer, regardless of DNA amplification and mutation." (PMID 33937011, 2020). "In the past decades, CD133 and EpCAM have been widely studied as stem cell markers in liver cancer." (PMID 32850663, 2020). "Our studies indicated that KLF4 could directly bind to the promoter of EpCAM and increase the number of EpCAM+/CD133+ liver cancer stem cells (LCSCs) in the HuH7 HCC cell line." (PMID 32408542, 2020).
liver cancer (continued). "Upregulated MYCN gene expression is restricted to specialized cell populations such as EpCAM+ cancer stem cells in liver cancer, regardless of DNA amplification and mutation." (PMID 33937011, 2020). "We further examined the expression of CBX8 in sorted primary EpCAM+ or CD133+ liver cancer cells." (PMID 30718464, 2019). "Yet, several surface markers have been proposed in the literature including CD24 for pancreatic and lung cancer, CD44 for breast, liver and head and neck cancers, CD133 (or Prominin) used for brain, colorectal, lung and liver cancers, and EpCAM/ESA for colorectal, and pancreatic cancers." (PMID 29391537, 2018). "Moreover, by performing survival analyses, we demonstrated that liver cancer patients with high levels of EpCAM expression have poor prognosis using the univariate Cox analysis model." (PMID 29497050, 2018). "The epithelial cell adhesion molecule (EpCAM) is over-expressed in some liver cancer cells and an RNA aptamer EpDT3 could specially target to EpCAM-positive cells." (PMID 29467932, 2018). "Moreover, immunohistochemistry demonstrates that EpCAM is highly expressed in 80% of H-ChC, implying the stemness of such liver cancer." (PMID 29497050, 2018). "A previous study demonstrated that nuclear accumulation of β-catenin may activate the expression of EpCAM in liver cancer cells, which is consistent with our findings." (PMID 28851352, 2017). "In addition, EpCAM+ HCC showed hepatic cancer stem cell-like traits, including self-renewal and differentiation, and were highly invasive and tumorigenic." (PMID 28137313, 2017). "Similarly, anti-c-Met and anti-epithelial cell adhesion molecule (EpCAM) have been evaluated for their ability to target gastric cancer and a wide range of solid tumors including breast, colon, and liver cancers, respectively." (PMID 27669301, 2016). "It has been speculated that HCCs displaying increased levels of EpCAM possess a more aggressive biologic behavior because they are a direct population derivative of hepatic cancer progenitor cells." (PMID 27447573, 2016). "As with previous studies of CD133 and EpCAM expression analysis in human liver cancer, HCC cell lines examined in this study exhibited a Gaussian distribution of KIAA1114 expression levels, rather than displaying a discrete, isolated population of KIAA1114+ cells." (PMID 24713374, 2014). "In conclusion, we identified miRNAs that are aberrantly expressed in EpCAM+ liver cancer cells." (PMID 23936298, 2013). "Similarly, the expression of oncogenic miRNAs like miR-21, miR-10b, let-7i, miR-34c, were increased more than 2 fold in EpCAM+ liver cancer cells; whereas miR-125b, miR-200a, miR-148b were most down-regulated." (PMID 23936298, 2013). "In addition, the miR-200a and miR-148b were significantly underexpressed in EpCAM+ liver cancer cells compared to fetal liver cells (P<0.05)." (PMID 23936298, 2013). "Taken together, our results suggest that the Hippo-YAP1 pathway might be involved in the pathogenesis of liver cancers with stemness, such as EpCAM(+)/K19(+) HCCs and cHC-CCs, which exhibit aggressive biological behavior." (PMID 24086533, 2013). "Surface markers, such as CD13, CD44, EpCAM, CD90, CD24, CD34, CD47, ICAM1, EpCAM, LGR5, and OV6, are widely recognized as markers of LCSCs, because of their association with proliferative capacity, self-renewal capacity, drug resistance, and recurrence of liver cancer." (PMID 38009775, 2023). "Given that overexpression of FGFR4 significantly correlates with EpCAM, a marker of hepatic cancer stem cells, within the fatty liver-steatosis-cirrhosis-HCC sequence, FGFR4 may have the ability to regulate cancer stem cells and lead to chemoresistance in HCC or other cancers." (PMID 30634399, 2019). "Moreover, liver cancer HepG2 cells is demonstrated to be a kind of EpCAM-overexpression cells." (PMID 29467932, 2018). "Furthermore, the liver cancer stem cells have been classified as two groups with EpCAM or CD90." (PMID 26556861, 2015).
liver cancer (continued). "Liver cancer stem-like cells (LCSLCs), charecerized by expression of CD133 and EpCAM, are critical for HCC initiation, metastasis, recurrence, and therapy resistance." (PMID 40677705, 2025). "Meanwhile, the protein levels of β-catenin and EpCAM in Huh7 and HepG2 cells were decreased with the knockdown of SLC1A4, approving the promoting role of SLC1A4 in EMT of hepatic cancer cells." (PMID 39949345, 2025). "Therefore, we first evaluated whether EpCAM-positive liver cancer cells would transform into CD90-positive liver cancer cells upon coculture with hepatic stellate cells (HSC) Lx2 and lung fibroblasts TIG3-20 to obtain a higher metastatic potential than CD90-positive liver cancer cells." (PMID 40253402, 2025). "The expression of liver cancer stem cell markers (ICAM1, CD47, CD24 and EPCAM) in HCC cells were determined by qPCR." (PMID 38169544, 2024). "Cholangiocarcinoma (CCA) is a primary liver cancer with a TME that is characterized by an abundance of CSCs and a demonstrated correlation of EpCAM expression with survival." (PMID 39513807, 2024). "A number of surface markers are known for CSCs in liver cancer (e.g., CD133, CD90, CD24, CD13, epithelial cell adhesion molecule /EpCAM/, aldehyde dehydrogenase /ALDH/, and hepatic progenitor cell marker OV-6)." (PMID 36672697, 2023). "To this end, we used flow cytometry to determine the intracellular accumulation of DOX in the liver cancer stem cells, which can be phenotypically defined by the double immunostaining of the cell surface CD133 and epithelial cell adhesion molecule (EpCAM)." (PMID 36358973, 2022). "Famous scholars from America and Japan have confirmed that peripheral blood EpCAM + CTC is the “seed” of liver cancer metastasis and recurrence and can be used as an independent predictor of metastasis and recurrence after liver cancer resection." (PMID 36175957, 2022). "We examined the heterogeneity of 17 liver cancer cell lines by performing cluster analysis of their expression of CD90 and EpCAM cancer stem cell markers." (PMID 34445353, 2021). "Restoration of EpCAM and Sox9 expression in JMJD2D-knockdown liver cancer cells rescued the self-renewal of LCSCs." (PMID 33434575, 2021). "In summary, liver cancer cell lines were distinctively clustered according to their expression of CSC markers, EpCAM and CD90." (PMID 34445353, 2021). "Cell markers that identify liver cancer stem cell populations include prominin-1 (CD133+), CD44+, CD13+, epithelial cell adhesion molecule (EpCAM+), CD90+, oval cell marker antibody 6 (OV6+), and aldehyde dehydrogenase (ALDH+)." (PMID 33669204, 2021). "We detected reduced expression levels of EPCAM, CD13, CD133, CD90.1 and CD44, which are known liver cancer stem cell markers (LCSC)." (PMID 34626204, 2021). "Epithelial cell adhesion molecule (EpCAM) is a single transmembrane glycoprotein overexpressed in various tumor types, and is also known as a representative marker of CSC status in liver cancer." (PMID 34671766, 2021). "In our study, 17 liver cancer cell lines were classified into clusters (EpCAM+, CD90+ and Neutral) according to their expression of CSC markers, EpCAM and CD90." (PMID 34445353, 2021). "The examination of liver cancer specimens demonstrated that HBx and TGF-β1 expression was positively correlated with epithelial cell adhesion molecule (EpCAM) and cluster of differentiation 90 (CD90)." (PMID 31740785, 2020). "We examined the liver cancer stem cell or progenitor markers (AFP, CD133, EPCAM, and KRT19), and hepatocyte terminal differentiation markers (ALB, G6PC, CYP3A4, and HNF4A) in subgroup of patients with different SOX signature scores." (PMID 31462277, 2019). "Liver CSCs are a small population of liver cancer cells and can be identified by series liver CSC markers, including epithelial cell adhesion molecule (EpCAM), CD24, CD90, CD133, and OV6." (PMID 31885628, 2019).
liver cancer (continued). "As expected, a higher expression level of EpCAM and CD133 was detected in DEN + MSC (Ps) group, compared with DEN group, indicating that MSCs facilitated the stem cell property of liver cancer cell." (PMID 29497038, 2018). "A number of markers, including CD13, CD44, CD24, CD90, CD133, EpCAM, DLK1, ALDH1 can be used to identify liver cancer stem cells." (PMID 28930164, 2017). "To address this issue, we determined the expression level of ZFX in EpCAM+ subpopulation sorted from cultured HCC cell lines (SMMC‐7721, HepG2, and Huh7) or primary liver cancer cells." (PMID 28156061, 2017). "Hepatic cancer stem cells (HCSCs) represent a subpopulation of cells positive for different markers including CD133, CD90, and EpCAM." (PMID 27118975, 2016). "It is of note that various markers have been identified for hepatic cancer stem cells, including CD133, CD90, and EpCAM." (PMID 27118975, 2016). "Our results demonstrated that ectopic expression of CD90 induced the expression of liver cancer stem cell markers, including CD133, CD24, and EpCAM." (PMID 26556861, 2015). "Liver CSC markers include EpCAM, CD133, CD90, CD44, CD24, CD13, and OV6, some of these markers are considered functional with highly invasive, metastasis, chemotherapy resistant of liver cancer." (PMID 26540347, 2015). "Nonmetastatic EpCAM-positive liver cancer cells transplanted into immunodeficient mice together with CD90-positive liver cancer cells metastasize to the lungs." (PMID 40253402, 2025). "In our previous study, we used EpCAM and CK18 to identify epithelium-derived tumor cells in the blood, and Her-2, CA-199, and αAFP for specific types of tumors such as breast, pancreatic, colon, or liver cancer." (PMID 39125505, 2024). "Thus, we clustered the cell populations into three groups with 3_Positive (CD24+EPCAM+CD133+) LCSCs, 3_Negative (CD24−EPCAM−CD133−) liver cancer cells and other cells, respectively." (PMID 37466793, 2023). "Furthermore, EpCAM+ ASGPR1+ and annexin V+ were increased in liver cancer (HCC and CCA) compared to cirrhotic patients." (PMID 36555854, 2022). "However, significant induction of hepatic cancer stem cell markers (MDR1, EPCAM, CD44 and CD133) in the tumors and surrounding liver tissue was attenuated upon GKT771 treatment." (PMID 33485364, 2021). "We also confirmed that our sorted EpCAM−/CD133− or EpCAM+/CD133+ cell populations are not enriched for other common liver cancer stem cell markers CD44 or CD90." (PMID 33524223, 2021). "Doxorubicin treatment induced senescence in both EpCAM+/CD133+ liver cancer stem cells and EpCAM−/CD133− nonstem cells." (PMID 33524223, 2021). "The most progress regarding a practicable use of large EVs has been achieved with the determination of large EVs positive for Annexin V, epithelial cell adhesion molecule (EpCAM), CD133 and asialoglycoprotein receptor 1 (ASGPR1) as a highly specific parameter for liver cancers diagnosis." (PMID 33080904, 2020). "To isolate L‐CSCs and non‐CSCs from HCC cell lines, we used three L‐CSCs surface markers, CD13, CD133 and EpCAM, to enrich triple‐positive and triple‐negative liver cancer cells from Huh7.5.1, Hep3B and PLC/PRF/5 cells by FACS." (PMID 32662250, 2020). "Moreover, the up-regulation of some genes related to the stemness of cancer cells, such as EpCAM, CD133, CD44, Oct4, Nanog, KLF4 and Sox4, in USP16-depleted liver cancer cells also suggests a stemness-suppressing role for USP16." (PMID 27633997, 2016). "EpCAM+ HCC cells, particularly Huh1 cells, can efficiently form organoid-like spheroids with features of glandular epithelium in vitro, which include acinar morphogenesis, but are chemoresistant and have elevated metastases in orthotopic liver cancer models." (PMID 26880118, 2016). "In addition, we have shown recently that ABCB5 regulated hepatic cancer stem cell markers CD133 and EpCAM." (PMID 22194816, 2011).
liver cancer (continued). "However, there were also some stromal CTCs in liver cancer patients, leading to low expression or even lack of EpCAM in some CTCs." (PMID 39280341, 2024). "However, EpCAM+ HCC1 and Huh7 cells as well as CD90+ HCC-derived SK-HEP1 cells rapidly developed resistance against the combined treatment with AKT and mTOR inhibitors in orthotopic liver cancer models in mice." (PMID 35454789, 2022). "Moreover, flow cytometry analysis of stem cell surface markers commonly used for isolating liver cancer stem cells demonstrated that, while expression of CD44 and CD90 remained unchanged upon Dox treatment, EpCAM + cell population significantly increased in both Dox‐treated LCSCs and nonstem cells." (PMID 33524223, 2021). "We propose that the promotion of miR-181 driven by HBx in HCCs could influence the beta-catenin pathway and promote EpCAM expression by suppressing PTEN protein expression, which may have revealed a novel regulatory link between miR-181a and human EpCAM(+) liver cancer stem/progenitor cells." (PMID 28053323, 2017). "In addition, Saito and colleagues reported using flow cytometric analysis that metformin treatment significantly reduces the number of tumor-initiating epithelial cell adhesion molecule (EpCAM)-positive HCC cells, which are considered as hepatic cancer stem cells." (PMID 25879666, 2015). "However, the expression levels of these miRNAs were not significantly changed between EpCAM− liver cancer cells and EpCAM− fetal liver cells (P>0.05)." (PMID 23936298, 2013). "In this study, we investigated senescence‐associated stemness and its related implications in EpCAM+/CD133+ liver cancer stem cell (LCSC) and EpCAM−/CD133− nonstem cell populations in HuH7 cell line." (PMID 33524223, 2021). "Although there is no international consensus abouty an ideal marker for liver cancer stem cells, the most promising seem CD90, a marker of oval cells, CD133 and EpCAM." (PMID 28930164, 2017). "Recently, in primary hepatic cancer samples the relative cellular expression of CD90 and EpCAM was analyzed: CD90 positivity does not overlap with EpCAM positivity." (PMID 28930164, 2017). "In the isolated cells from human liver cancer cell line Huh7, Cells with CD133+/CD44+/CD24+/EpCAM+(HLCSC) was 15.3 ± 5.26%, Cells with CD133−/CD44−/CD24−/EpCAM-(non-HLCSC) was 5.23 ± 2.56% and others was 79.43 ± 5.19% (P < 0.01, respectively)." (PMID 26513297, 2015). "Western blotting showed that liver cancer stem cells CD133, CD44, CD24 and EpCAM were expressed in human liver cancer stem cells(HLCSC), as well as CD133, CD44, CD24 and EpCAM were not expressed in liver cancer unstem cells (non-HLCSC)." (PMID 26513297, 2015). "A recent example has been provided by Julich-Haertel and colleagues, who have found that MPs positive for AnnexinV, EpCAM, and ASGPR1 may help distinguish between subjects with liver cancer and subjects with cirrhosis but no detectable liver malignancy." (PMID 28498353, 2017). "But more importantly, the pattern of increasing expression of FGF19, FGFR4 and EpCAM within the HCC, suggests a mechanistic interaction between the fibroblast growth factor/receptor and hepatic cancer stem cells, which has not been described prior to this study." (PMID 27447573, 2016).